RNU6-855P (RNA, U6 small nuclear 855, pseudogene)
Gene: Small nuclear RNA gene on chromosome 9 (112,137,797 to 112,137,900, forward strand). Ensembl gene ENSG00000222327.
Homologues: Orthologues: chimpanzee U6 (99% identical), macaque U6 (91% identical), rabbit U6 (80% identical), guinea pig U6 (76% identical), mouse Gm22364 (74% identical), pig U6 (74% identical), dog U6 (72% identical). Paralogues in human: RNU6-797P (87% identical), RNU6-266P (86% identical), RNU6-727P (86% identical), RNU6-1094P (85% identical), RNU6-1209P (85% identical), RNU6-1287P (85% identical), RNU6-189P (85% identical), RNU6-272P (85% identical), RNU6-1091P (84% identical), RNU6-1331P (84% identical), RNU6-242P (84% identical), RNU6-500P (84% identical), and 1290 more.